CTTN (cortactin)
Diseases named in the same sentence as CTTN in open-access papers (continued):
Sharing a sentence is not in itself a finding about the gene and the disease.
pancreatic cancer (12 papers, 2010 to 2025). "Cortex protein (CTTN), an actin nucleation-promoting factor, has been reported to be up-regulated in pancreatic cancer cells and is associated with migration, invasion, and metastasis." (PMID 40507156, 2025). "Moreover, cortactin and fascin-1 are overexpressed in the tissues of patients with advanced pancreatic cancer, and this is associated with low rates of long-term survival." (PMID 34194957, 2021). "EZR links the plasma membrane to the actin cytoskeleton and has been found to regulate podosomal rosette formation together with CTTN in pancreatic cancer cells." (PMID 32984315, 2020). "By Kaplan–Meier analysis on pancreatic cancer, the level of each gene is linked to survival probability, with high expression for E2F1, PRMT5 and cortactin/CTTN linked to poor survival." (PMID 32709847, 2020). "Subsequently, the expression of Cortaction in pancreatic cancer cells with shGirdin transfection was examined, and the results showed that protein expression of Cortactin was decreased while the mRNA expression of Cortaction showed no significant change." (PMID 32369440, 2020). "Ezrin can interact with cortactin to form podosomal rosettes in pancreatic cancer cells, thereby playing a role in pancreatic cancer invasion." (PMID 20569470, 2010). "Moreover, Cortactin or Tks5 were immunostained with E‐cadherin in human pancreatic cancer BxPC‐3 cells that had been ectopically implanted in mice." (PMID 40366255, 2025). "Thus, blockade of destrin, cortactin, and fascin-1 overexpression will slow down pancreatic cancer progression." (PMID 34194957, 2021). "Finally the rescue experiments were carried out, the results displayed that overexpression of Cortactin significantly abolished the anti-tumor effect of shGirdin on pancreatic cancer cells." (PMID 32369440, 2020). "A previous study also detected a dramatic reduction in the number of pancreatic cancer cells with podosomal rosettes after ezrin RNAi treatment and reported that formation of podosomes and their rosettes was driven by an ezrin–cortactin interaction, which has a role in pancreatic cancer invasion." (PMID 23357878, 2013). "Moreover, we found that overexpression of Cortactin could rescue the effect of shGirdin on proliferation, apoptosism, migration and invasion of pancreatic cancer cells." (PMID 32369440, 2020). "Invasive pseudopods that we defined in these pancreatic cancer cells highly expressing ARL4C consisted of similar molecules, including cortactin, ARPC2, IQGAP1, and MMP14, which are involved in invadopodia functions." (PMID 34590580, 2021). "Meanwhile, components of invadopodia, such as cortactin and ARPC2, were localized at the tips of protrusions defined above, with ARL4C, suggesting that the protrusions might contribute to invasive phenotypes of pancreatic cancer cells and ARL4C functions there." (PMID 34590580, 2021).
breast tumors (11 papers, 2006 to 2023). "We next analyzed patient breast tumor databases for a correlation between protein abundance levels of Abl, Arg, and cortactin." (PMID 29774130, 2018). "When we used cortactin and Tks5 as invadopodium markers in breast tumor cells, we found that knocking down PTP1B with siRNA increased invadopodium-associated ECM degradation and the number of mature invadopodia per cell." (PMID 27824079, 2016). "IHC staining was assessable in 258 of the 500 primary breast tumors for cortactin and in 295 for FADD." (PMID 18823530, 2008). "In summary, findings could suggest the binary settings of pro-metastatic genes, including CTTN-ROCK and RhoA-ROCK in association with a breast tumor diagnosed with infiltration into axillary lymph nodes which is representative of local breast metastasis." (PMID 33407452, 2021). "Thus, our results suggest that trastuzumab and a TCF/β-catenin inhibitor could be used in combination to treat HER2+ breast tumors expressing high levels of CTTN." (PMID 36831511, 2023). "It was previously shown that Arg mediates EGF-induced cortactin tyrosine phosphorylation in invadopodia, leading to barbed end generation and consequent actin polymerization, ECM degradation, and matrix-proteolysis dependent breast tumor cell invasion." (PMID 34440806, 2021). "From this study, we can conclude that development of (pre-malignant) breast tumors in either wild type or MMTV-cyclin D1 mice was not augmented due to mammary gland targeted overexpression of human cortactin." (PMID 16536875, 2006). "Our results demonstrate that mammary gland targeted cortactin did not affect mammary epithelial cell morphology and did not provide proliferative advantages in the development of (pre-malignant) breast tumor in either WT or MMTV-cyclin D1 transgenic mice." (PMID 16536875, 2006). "From this study, we conclude that development of (pre-malignant) breast tumors in either wild type or MMTV-cyclin D1 mice was not augmented due to mammary gland targeted overexpression of human cortactin." (PMID 16536875, 2006). "In summary, our data suggest that the MMTV-cortactin transgenic mice neither develop breast tumors nor accelerate MMTV-cyclin D1-induced mammary tumorigenesis on top of the causal MG tumors that arose in the aged FVB/N mice." (PMID 16536875, 2006).
hepatocellular carcinoma (11 papers, 2013 to 2026). A malignant tumor that arises from hepatocytes. "Overexpression of cortactin is associated with increased invasiveness of hepatocellular carcinoma cells." (PMID 24551190, 2014). "ZMYM3 promotes hepatocellular carcinoma metastasis by upregulating CTTN and inducing invadopodia formation." (PMID 41775697, 2026). "Cortactin is an important regulator involved in invasion and migration of hepatocellular carcinoma (HCC)." (PMID 23518204, 2013). "In hepatocellular carcinoma, MPZL1 recruits SHP-2 to phosphorylate Src kinase at Tyr426, subsequently leading to cortactin phosphorylation, which promotes the migration of hepatocellular carcinoma cells." (PMID 40223054, 2025). "After LINC00511 overexpression, the colocalization of F-actin and cortactin was analysed by fluorescence confocal microscopy, and the results indicated that LINC00511 significantly induced invadopodia formation in hepatocellular carcinoma cells." (PMID 34088337, 2021).
glioblastoma (9 papers, 2011 to 2024). The most malignant astrocytic tumor (WHO grade IV). "Src kinase-associated phosphoprotein 2 (SKAP2) is an adaptor protein for SFKs that interacts with WAVE2 and cortactin, antagonizing their adhesion-induced translocation to the membrane and inhibiting glioblastoma cell migration." (PMID 39354505, 2024). "In glioblastoma, cytoskeletal dynamics, which is required for cellular motility and invasiveness, seems to be dependent upon cortactin interaction with cytoskeletal components." (PMID 31986121, 2020). "The importance of intracellular targeting of cortactin has been shown with a cell-permeable peptide that binds cortactin, and inhibits the invasion of a range of cancers including glioblastomas." (PMID 30949052, 2019). "Glioblastoma migration affected by WAVE2, SKAP2, cortactin, and FYN was also discussed earlier in relation to ABI1 and ABL1, linking EGFR and SFK signaling directly to ARP2/3-mediated actin polymerization." (PMID 39354505, 2024). "Because we showed a decrease in the migration capacity of glioblastoma cells under treatment with miR‐218 in our studies, we could conclude then that these changes might be the result of the impact of miR‐218 on CDC42, STAT3, EGF and CTTN." (PMID 35702951, 2022). "Here, we used immunolabeling and imaging approaches to demonstrate that glioblastoma cells digest gelatin at sites of invadopodia (ventral protrusions containing actin, cortactin, MT1-MMP and TKS5) and at FAs at the leading edge of the cells (containing actin, cortactin and P-FAK)." (PMID 31947771, 2020).
lymph node metastasis (9 papers, 2008 to 2023). "Consistent with the central role of cortactin in regulating invadopodia formation, clinical studies have shown that cortactin overexpression is associated with local invasion, lymph node metastasis, and/or distal metastases." (PMID 36420735, 2023). "The results showed that CTTN overexpression was significantly associated with lymph node metastasis (P = 0.000) and pathological stage (P = 0.000)." (PMID 24551190, 2014). "We found that high tumoral CORTACTIN expression associated with poor survival, higher T-stage, and higher lymph node metastasis (N-stage) in these patients." (PMID 23423155, 2013). "Located at chromosomal region 11q13, an area frequently amplified in HNSCC, cortactin has consistently been associated with more aggressive and invasive tumors, lymph node metastasis and poor clinical outcome in HNSCC." (PMID 24212639, 2011). "This study found that gene amplification correlated significantly to mRNA and protein expression, with cases containing strong cortactin staining significantly associated with lymph node metastasis." (PMID 24212639, 2011). "Recently, in a small number of HNSCCs, 11 out of 39 (28%) cases, cortactin overexpression determined by immunohistochemistry correlated with lymph node metastasis and CTTN gene amplification." (PMID 18268492, 2008). "Although lymph node metastasis has been reported as an important clinical prognosticator, cortactin expression (HR=13.14; 95% CI, 3.04–56.87; P=0.0006) correlated stronger to increased DSM than lymph node metastasis (HR=3.16; 95% CI, 1.29–7.75; P=0.012)." (PMID 18268491, 2008). "We show that both cortactin and lymph node metastasis are good predictors for DSM using a multivariate model independent of cyclin D1 and FADD." (PMID 18268491, 2008). "Both cortactin expression and lymph node metastasis were significantly related to increased DSM, implying they are both prognostic factors." (PMID 18268491, 2008). "Moreover, overexpression of cortactin (CTTN) was observed in 126/198 (63.6%) of ESCC cases and was significantly associated with lymph node metastasis (P = 0.000), pathologic stage (P = 0.000) and poor survival (P<0.001) of ESCC patients." (PMID 24551190, 2014). "This implies a correlation between lymph node metastasis and cortactin, as suggested previously." (PMID 18268491, 2008). "Since lymph node metastases have been shown to be an important prognostic factor for DSM, we assessed the additional prognostic value of cyclin D1, FADD and cortactin in late stage LSCC." (PMID 18268491, 2008). "The mean expression of cortactin was significantly higher in the group of patients with lymph node metastases (42/55 cases) compared to those without lymph node metastases (13/55 cases) (Wilcoxon two-sample test, rs = 0.1076, P = 0.0165)." (PMID 29986736, 2018). "Secondly, we evaluated whether protein expression of FADD, cyclin D1 and cortactin were related to increased DSM and lymph node metastasis." (PMID 18268491, 2008). "However, also within the lymph node metastasis positive group, high cortactin expression identifies patients with significantly increased DSM, whereas low cortactin expression identifies a group of patients with a good prognosis for survival." (PMID 18268491, 2008). "Furthermore, the mean expression of cortactin was significantly lower in the group of patients with lymph node metastases compared with those without lymph node metastases." (PMID 29986736, 2018). "Furthermore, expression of cortactin, cyclin D1 and more recently FADD, have been described separately as potential predictors for increased disease-related mortality, for lymph node metastasis and poor prognosis." (PMID 18268491, 2008).
ovarian carcinoma (8 papers, 2011 to 2023). A malignant neoplasm originating from the surface ovarian epithelium. "In ovarian cancer cells, StarD13 depletion also led to an increase in cortactin-labeled and WASP-labeled potential invadopodia, while Cdc42 depletion completed abolished any of these structures." (PMID 34958986, 2022). "HA binding to CD44 has been shown to promote ovarian cancer cell migration by recruiting Src and promoting cortactin-mediated cytoskeleton function." (PMID 31898491, 2020). "The HS1 homolog CTTN is also expressed in ovarian cancer and is reported to contribute to cell migration." (PMID 30220969, 2018). "In summary, our results conclusively establish for the first time that Hax-1 is critically required for the Rac1-cortactin interaction and subsequent invasive migration of ovarian cancer cells." (PMID 25053987, 2014). "Cortactin is overexpressed in many types of human cancers, including head and neck squamous carcinomas and colorectal, gastric, hepatocellular, breast and ovarian cancers." (PMID 24551190, 2014). "Cortactin is frequently overexpressed in many types of human cancers, including head and neck and esophageal squamous carcinomas, colorectal, gastric, hepatocellular, breast and ovarian cancers." (PMID 29986736, 2018). "Thus, the results presented here define a critical scaffolding role for Hax-1 in LPA-stimulated Rac1-cortactin interaction and subsequent ovarian cancer cell migration." (PMID 25053987, 2014). "Our results also indicate that the competitive inhibition of the interaction between endogenous Hax-1 and Rac1 or Hax-1 and cortactin by the ectopic expression of any of these domains led to a decrease in LPA-stimulated migration of ovarian cancer cell line SKOV3." (PMID 25053987, 2014). "Thus our results presented here describe for the first time that Hax-1 interaction is required for the association between Rac1 and cortactin and that these multiple interactions are required for the LPA-stimulated migration of SKOV3 ovarian cancer cells." (PMID 25053987, 2014).
esophageal cancer (7 papers, 2014 to 2025). A primary or metastatic malignant neoplasm involving the esophagus. "The CTTN exon 11 skipping/inclusion event was observed both in esophageal cancer samples and survival-related SFs knockdown data." (PMID 40282339, 2025). "CTTN is closely related to prognosis in head and neck cancer, esophageal cancer, thyroid cancer, and glioma, among others." (PMID 31927533, 2020). "We then validated CTTN exon 11 inclusion in paired esophageal cancer samples." (PMID 40282339, 2025). "Additionally, CTTN exon 11 inclusion was correlated with poor prognosis in esophageal cancer." (PMID 40282339, 2025). "Exon 11 skipping of CTTN occurred after knockdown of most survival-related SFs (CRNKL1, SNRPB2, PPWD1, RBMX2, and DDX46), while exon 11 inclusion was observed in esophageal cancer in comparison to normal tissue, both in the TCGA database and in our own full-length sequencing data." (PMID 40282339, 2025).
head and neck cancer (7 papers, 2013 to 2022). A primary or metastatic malignant neoplasm affecting the head and neck. "For instance, integrin β1/FAK/cortactin signaling was essential for human head and neck cancer resistance to radiotherapy." (PMID 29930482, 2018). "Here, we investigated the role of CORTACTIN in the pathophysiology of orohypopharynx carcinoma – one of the major subtypes of head and neck cancer." (PMID 23423155, 2013). "CTTN was closely correlated with the prognosis of head and neck cancer and glioma." (PMID 35121801, 2022). "Moreover, in head and neck cancer, FOXP3 may cooperate with the inflammation factor COX2 and with the migration/invasion factors AHNAK and cortactin to promote tumor progression." (PMID 26305693, 2015).
laryngeal carcinoma (7 papers, 2008 to 2019). Carcinoma that arises from the laryngeal epithelium. "In HNC, amplification of CORTACTIN gene has been linked to poor clinical outcome mainly in patients with laryngeal carcinoma." (PMID 23423155, 2013). "In line with this, we described in a previous report that amplifications of CCND1 and CTTN strongly and significantly predict laryngeal cancer development." (PMID 26498851, 2015). "Among the HNC subtypes, CORTACTIN has been mainly proposed as a potential biomarker for laryngeal carcinoma." (PMID 23423155, 2013). "In this paper, we compared, using immunohistochemical analysis for cyclin D1, FADD and cortactin in a series of 106 laryngeal carcinomas which gene correlates best with lymph node metastases and increased disease-specific mortality." (PMID 18268491, 2008). "Of genes located in the 11q13 amplicon, cortactin expression is the best predictor for shorter disease-specific survival in late stage laryngeal carcinomas." (PMID 18268491, 2008). "We also demonstrated that the interaction of integrin β1 with CD147 could activate the downstream FAK/cortactin signaling pathway, subsequently enhancing the malignant properties of laryngeal cancer cells." (PMID 29930482, 2018). "Our study confirmed that FAK/cortactin pathways could be suppressed by integrin β1-knockdown, implying their participation in the invasion and radioresistance of laryngeal cancer cells." (PMID 29930482, 2018). "Furthermore, several studies demonstrated a correlation between a high cortactin expression and a poor prognosis in several types of human neoplasms such as oesophageal squamous cell carcinoma, pancreatic and colorectal adenocarcinoma and laryngeal carcinoma." (PMID 27911942, 2016).
B-cell chronic lymphocytic leukemia (6 papers, 2018 to 2022). "Moreover; high cortactin expression was reported in B-cell chronic lymphocytic leukemia, and is associated with poor prognosis and increased chemotaxis; and is correlated with treatment failure and relapse." (PMID 33773540, 2021). "Cortactin is an actin-binding protein involved in cell adhesion and migration that is overexpressed in many solid tumors and in adult B-cell chronic lymphocytic leukemia." (PMID 30573781, 2019). "In cancer, it was shown that CTTN was over-expressed in B-cell lymphocytic leukemia cells, and that it played a role in the Lyn signaling pathway." (PMID 30220969, 2018). "Cortactin is upregulated in several cancers to trigger cell migration and invasiveness, and both cortactin and HS1 are related to poor prognosis in adult B-cell chronic lymphocytic leukemia (B-CLL), and linked to high levels of the known risk factors ZAP70 and CD38." (PMID 30573781, 2019).
bladder cancer (5 papers, 2002 to 2025). "In bladder carcinoma, CTTN may be involved in the regulation of actin-based extravasation through invadopodia formation." (PMID 31108958, 2019). "Because SIRT2 has also been suggested to be involved in cortactin deacetylation in A549 cells and work synergistically with HDAC6 to promote cell migration and invasion in bladder cancer, we examined the role of SIRT2 in dendrite development in vitro." (PMID 32711564, 2020). "For example, in bladder cancer cells, Capsaicin reduces the deacetylase of SIRT1, enhances the acetylation of cortactin and β-catenin, thereby reducing the activation of MMP-2 and MMP-9, and ultimately leads to the migration disturbance of bladder cancer cells." (PMID 40007993, 2025).
oral squamous cell carcinoma (5 papers, 2020 to 2025). "The SHANK2 and CTTN genes are in close proximity (30 kb) and are often co-amplified in oral squamous cell carcinoma." (PMID 32252688, 2020). "Co-amplification of CTTN, SHANK2 and CCND1 genes has been reported previously in oral squamous cell carcinoma." (PMID 32252688, 2020).